PBRM1 (polybromo 1)
Diseases named in the same sentence as PBRM1 in open-access papers (continued):
Sharing a sentence is not in itself a finding about the gene and the disease.
pancreatic cancer (7 papers, 2013 to 2025). "In this study, we demonstrate that the chromatin regulator PBRM1 binds to the vimentin promoter region and epigenetically regulates its expression in pancreatic cancer." (PMID 40454484, 2025). "At the 2-week time point, control (KPF) animals developed well-differentiated PDACs, whereas Pbrm1-null mice exhibited significantly more poorly differentiated PDACs or undifferentiated carcinomas of the pancreas than control mice." (PMID 40454484, 2025). "ARID1A, ARID1B, PBRM1, SMARCA2, and SMARCA4 are all components of the SWI/SNF complexes, and were shown by genomic sequencing studies to be mutated in pancreatic cancer." (PMID 27999365, 2016). "Putative DNA binding subunits ARID1A, ARID1B, and PBRM1, enzymatic subunits SMARCA2 and SMARCA4, and ARID2 have been shown to be mutated in pancreatic cancer." (PMID 27999365, 2016). "Our previous report demonstrated a negative association of PBRM1 expression with cancer stemness in several types of solid tumors, including kidney and pancreatic cancers, although mechanistic studies are missing." (PMID 36674511, 2023). "In pancreatic cancer, recent whole genomic sequencing also revealed pathogenic mutations and structural variants in several epigenetic regulator genes including KDM6A, ARID1A, ARID1B, PBRM1, SMARCA2, SMARCA4, and MLL2." (PMID 27999365, 2016). "On tissue NGS of immunotherapy-treated, SWI/SNF-altered pancreatic cancer patients, 7 patients harbored an ARID1A alteration (77%); 2 harbored an ARID1B mutation (22%); 3 harbored a SMARCA4 mutation (33%); 1 harbored a SMARCB1 mutation (11%); and 1 harbored a PBRM1 mutation (11%)." (PMID 34375311, 2021). "The previous reports, together with this study, indicate that PBRM1, ARID1A, and SMARCB1 play tumor-suppressive roles and inhibit EMT in pancreatic cancer." (PMID 40454484, 2025). "Pancreatic cancer genomic characterization through TCGA found SWI/SNF alterations in 10% of samples (ARID1A, 6%; PBRM1, 4%)." (PMID 34375311, 2021). "In summary, the current analysis suggests that a subgroup of patients with pancreatic cancer and alterations in SWI/SNF complex chromatin remodeling genes, such as ARID1A, ARID1B, PBRM1, SMARCA4, and SMARCB1, can respond to ICI." (PMID 34375311, 2021).
schizophrenia (7 papers, 2015 to 2025). A major psychotic disorder characterized by abnormalities in the perception or expression of reality. "This region harbours genes including ITIH4, NEK4, GNL3 and PBRM1 that have previously been linked mechanistically to schizophrenia and related brain changes at cellular and whole brain scales." (PMID 38016951, 2023). "The genomic region of chromosome 3p21.1 contained several genes pleiotropically associated with both SA and schizophrenia, including PBRM1, NEK4, GNL3, ITIH4 and NISCH." (PMID 38016951, 2023). "Furthermore, the PBRM1 gene has been associated with susceptibility to schizophrenia and bipolar disorder." (PMID 27142060, 2016). "Many risk genes shared by schizophrenia and BD have been reported to affect dendritic spine morphogenesis, such as NEK4, GNL3, PBRM1, and GLT8D1." (PMID 37443018, 2023). "Recently, a study found that the genetic variants in the 3p21.1 region affect expression of NEK4, GNL3, and PBRM1 in the frontal cortices, which in turn affected dendritic spines, cognitive function, schizophrenia, and bipolar disorder." (PMID 34291596, 2021). "Our finding that these proteins all interact with BRD1 provides a novel line of evidence implicating the network of BRD1, PBRM1, and 14-3-3 proteins with schizophrenia and bipolar disorder." (PMID 27142060, 2016). "These PPIs are of particular interest since genetic association studies have previously implicated YWHAE, YWHAH, and YWHAZ with schizophrenia and bipolar disorder and the PBRM1 locus has surpassed genome-wide significance in both schizophrenia and bipolar disorder GWASs." (PMID 27142060, 2016). "Sequence variants in other BAF complex genes are associated with other neurodevelopmental disorders including SMARCC1/2, PBRM1, ARID1A/B and SMARCA4 in ASD, PBRM1 and ARID1B in schizophrenia, SMARCB1 in Kleefstra syndrome, and ARID1A/B, SMARCA4, SMARCB1, and SMARCE1 Coffin-Siris syndrome (CSS)." (PMID 31288860, 2019). "Interestingly, HNRNPH1 binding affinity and splicing can be modulated by genome-wide significant SNPs associated with bipolar disorder, major depressive disorder, and schizophrenia, including rs1006737 (CACNA1C), rs2251219 (PBRM1), and rs1076560 (DRD2)." (PMID 26658939, 2015).
bipolar disorder (6 papers, 2015 to 2025). A disorder of the brain that causes unusual shifts in mood, energy, activity levels and the ability to carry out day-to-day tasks. "Common genetic polymorphisms at PBRM1 (also named 3p21.1 locus) have been implicated in susceptibility to bipolar disorder, as well as major depression and schizophrenia." (PMID 34294844, 2021). "Another genetic association study also found 3p21.1 (including PBRM1, strong linkage disequilibrium made it difficult to pinpoint the risk genes) as risk loci for bipolar disorder (BD), SCZ and psychosis." (PMID 32066673, 2020). "Among the four sex-specific loci identified in the current study, two, PBRM1 and ASTN2, have been involved in susceptibility to bipolar disorder and other psychiatric phenotypes." (PMID 34294844, 2021).
colorectal cancer (6 papers, 2020 to 2025). A primary or metastatic malignant neoplasm that affects the colon or rectum. "In colorectal cancer, the low expression of PBRM1 was an independent risk factor for poor patient prognosis." (PMID 40093909, 2025). "Although PBRM1 showed a high frequency of mutations in colorectal cancer and is strongly associated with poor prognosis, the role and potential mechanisms of the SWI/SNF complex and PBRM1 mutations in immunotherapy in colorectal cancer remain unclear." (PMID 40093909, 2025). "Furthermore, fluorescence staining of 25 colorectal cancer samples treated with PD-1 immunotherapy exhibited a significant abundance of infiltrating CD8+ T cells in PBRM1-deficient tissues compared to the PBRM1 wild-type group." (PMID 40093909, 2025). "The prevalence of PBRM1 deficiency is only about 10% in colorectal cancer." (PMID 40093909, 2025). "Our study identifies PBRM1 as a potential molecular target for enhancing immunotherapy in colorectal cancer." (PMID 40093909, 2025). "We investigated the effect of PBRM1 mutations on the biological function of tumor cells using the CRISPR-Cas9 gene editing system to introduce deletion mutations in human and mouse colorectal cancer cells, HCT116 and CT26." (PMID 40093909, 2025). "Immunohistochemical staining of 208 human colorectal cancer tissues similarly showed that PBRM1 expression inversely correlated with the abundance of CD8+ T cell infiltration." (PMID 40093909, 2025). "PBRM1 is expressed at low levels in numerous tumors, including colorectal cancer, and positively correlates with the abundance of immune cells in the mesenchyme." (PMID 40093909, 2025). "In colorectal cancer, truncating mutations in ARID1A or PBRM1 have been linked to increased TMB, robust cytolytic immune infiltration, and durable responses to ICIs." (PMID 41438758, 2025). "Given the significant heterogeneity of tumor microenvironment among various types of cancers, we focused on two cancer types with the most POL&PBRM1 patients: colorectal cancer and endometrial cancer." (PMID 39218995, 2024). "In addition, we found that silencing MUC1-C in (i) NCI-H660 neuroendocrine PC (NEPC) cells, (ii) BT-549 triple-negative breast cancer and (ii) SW620 colorectal cancer (CRC) cells results in downregulation of PBRM1, ARID2, and BRD7." (PMID 34163028, 2021). "In colorectal cancer, the POL&PBRM1 group had more CD4+ memory T cells, and CD8+ T cells (CD8+ naive T cells, CD8+ effector memory T cells, and CD8+ central memory T cells)." (PMID 39218995, 2024). "We used immunohistochemical staining to examine 25 colorectal cancer samples treated with PD-1 immunotherapy and found a strong association between the lack of protein expression and LOF of PBRM1 with immunotherapy sensitivity." (PMID 40093909, 2025).
lung adenocarcinoma (6 papers, 2014 to 2025). A carcinoma that arises from the lung and is characterized by the presence of malignant glandular epithelial cells. "Among these were mutations in two well-known ccRCC cancer driver genes (VHL and PBRM1) and in EPHA4, a lung adenocarcinoma driver gene." (PMID 31212796, 2019). "We identified alterations in genes involved in chromatin remodeling (PBRM1, SETD2), oxidative stress (CUL3, SOD2), immune response (CSMD3, SYK), and gamma-aminobutyric acid receptor signaling (GABRD, GABRG1) in lung adenocarcinoma." (PMID 24576404, 2014). "There was a significant decrease in PBRM1 RNA expression in cancer tissues compared to normal tissues, including bladder urothelial carcinoma (BLCA), breast invasive carcinoma (BRCA), colon adenocarcinoma (COAD), and lung adenocarcinoma (LUAD)." (PMID 40093909, 2025).
meningioma (6 papers, 2020 to 2025). A generally slow growing tumor attached to the dura mater. "PBRM1 mutations are relatively uncommon in meningiomas, but when present, they are associated with papillary subtypes and often have overlapping BAP1 mutations." (PMID 41199851, 2025). "Despite PBRM1 mutations rarely occurring in meningioma, this represents a potential therapeutic investigation." (PMID 41199851, 2025). "With our case study, we have begun to further explore the occurrence of PBRM1 mutations and subsequent outcomes in patients with meningiomas." (PMID 41199851, 2025). "PBRM1 genetic alterations are infrequent (2.8%) in meningiomas, and alterations are usually associated with high-grade meningiomas." (PMID 41199851, 2025). "Mutations in SMARCE1 (SWI/SNF-related matrix-associated actin-dependent regulator of chromatin subfamily B member 1), BAP1 (BRCA1 associated protein-1), and PBRM1 are associated with different meningioma histologic subtypes." (PMID 38695575, 2024). "As previously reported, 11 of 16 PBRM1 mutations (68.7%) occurred in meningioma with papillary histologic features." (PMID 33087175, 2020). "Our genomics analysis on meningioma patients demonstrated 90% (9/10) patients having PBRM1 mutations with unknown oncogenic significance." (PMID 41199851, 2025). "We add to the limited literature regarding PBRM1 mutations in meningiomas." (PMID 41199851, 2025). "In addition, we have recently reported frequent PBRM1 mutations in meningiomas with papillary histologic features." (PMID 33087175, 2020). "However, in a recent case series of 850 patients with meningiomas that were grade 1 (220/850, 26%), grade 2 (441/850, 52%), and grade 3 (176/850, 20%) (13 cases were not graded due to inadequate specimens), only 16 had an inactivating mutation in PBRM1 (1.9%)." (PMID 41199851, 2025). "The frequency (2.5%) of PBRM1 alterations in meningiomas in our analysis matches published literature." (PMID 41199851, 2025). "In our case, however, more than 80% of the samples that acquired 3p-loss (that overlapped BAP1 and PBRM1) without 22q-loss were grade I, extending a role for this driver to a broader spectrum of meningiomas that includes low grade lesions." (PMID 37805627, 2023). "In addition, 81% of BAP1 and 87.5% PBRM1 mutant meningiomas were classified as WHO grades 2 and 3 meningiomas." (PMID 33087175, 2020).
prostate carcinoma (6 papers, 2019 to 2024). A carcinoma that arises from epithelial cells of the prostate gland. "Under identical treatment conditions, AU-24118 demonstrated comparable degradation efficacy of SMARCA4 and PBRM1 to AU-15330 in VCaP prostate cancer cells." (PMID 38557192, 2024). "In this study, we utilized a PROTAC compound, AU-15330, that simultaneously degrades SMARCA4, SMARCA2, and PBRM1 and is toxic in enhancer-addicted prostate cancers." (PMID 37094128, 2023). "Although a tumor suppressor in some cancers, PBRM1 promotes prostate cancer growth and progression." (PMID 38390898, 2024). "Western blot analysis confirmed robust downregulation of direct targets (SMARCA2, SMARCA4, and PBRM1) and specific prostate cancer lineage proteins (AR, ERG, C-Myc, and PSA) after 5 d of AU-24118 treatment, whether administered alone or in combination with enzalutamide." (PMID 38557192, 2024). "In the study, MUC1-C induced PBRM1 by E2F1-mediated activation at its promoters, allowing MUC1-C to form a complex with NRF2 and PBRM1 on the NRF2 target SLC7A11 to drive its transcription in human prostate cancer stem cells." (PMID 38358974, 2024). "We further showed that degradation of these subunits, along with PBRM1, led to rapid and widespread chromatin compaction, perturbing essential oncogenic programs driven by transcription factors such as AR, FOXA1, and ERG in prostate cancer models." (PMID 38557192, 2024). "This implies that SMARCA4, rather than SMARCA2 or PBRM1, may be the critical target to perturb in the context of prostate cancer therapy." (PMID 38557192, 2024).
biliary tract cancer (4 papers, 2016 to 2023). "Polybromo-1 (PBRM1) loss of function mutations are present in a fraction of biliary tract cancers (BTCs)." (PMID 37400502, 2023). "In this study, PBRM1 knockdown in biliary tract cancer resulted in synergy with the drug efficacy of niraparib and olaparib in vitro." (PMID 37728655, 2023). "In clinical practice, the therapeutic efficacy of niraparib has been also reported in patients with advanced biliary tract cancer with PBRM1 mutant." (PMID 37728655, 2023).
bladder cancer (4 papers, 2015 to 2025). "For instance, the mRNA and protein levels of PBRM1 (Encoding BAF180 protein) in bladder cancer cells are conspicuously lower than those in normal cells, and the low expression of PBRM1 is associated with lower survival rates in bladder cancer patients." (PMID 39779467, 2025). "Univariate analysis indicated that reduced expression of PBRM1 was associated with tumor progression, emphasizing an important tumor suppressive role of PBRM1 in bladder cancer." (PMID 25978027, 2015). "As expected, there was also a significant association between PBRM1 expression and overall survival in patients with bladder cancer." (PMID 25978027, 2015). "Our data implicated that PBRM1 might suppress cyclin B1 and exert its tumor suppressing role by inducing cell cycle arrest in bladder cancer." (PMID 25978027, 2015). "In addition, low PBRM1 expression was associated with shorter overall survival in bladder cancer patients." (PMID 25978027, 2015). "PBRM1 (encoding BAF180 protein) is found to be mutated in 2%–10% of bladder tumours, and it exerts a suppressive effect on bladder cancer by inhibiting the activity of cyclin B." (PMID 39779467, 2025). "In bladder cancer cells, the mRNA and protein levels of PBRM1 are significantly lower than those in normal cells." (PMID 39779467, 2025). "A significant correlation with adverse OS was also seen in bladder cancer (n = 245; HR 11.85, p < 0.001); however, only three PBRM1 mutants comprised this group." (PMID 32820162, 2020). "We suggested that reduced expression of PBRM1 disrupts cell cycle control, in turn promotes cell proliferation and facilitates the development of bladder cancer." (PMID 25978027, 2015). "We examined the expression of PBRM1 in both human bladder cancer cell lines and normal uroepithelial cell line SV-HUC-1 by qRT-PCR and Western blotting." (PMID 25978027, 2015). "Then we analyzed the mRNA and protein expression of PBRM1 in 64 paired bladder cancer tissues and adjacent non cancerous tissues by qRT-PCR and immunohistochemistry." (PMID 25978027, 2015). "Compared with their non cancerous counterparts, significantly lower expression of PBRM1 mRNA was observed in 59.4% (38/64) of bladder cancer samples." (PMID 25978027, 2015). "In conclusion, we demonstrated for the first time that PBRM1 was present at low level in human bladder cancer tissues and cell lines." (PMID 25978027, 2015). "Our data indicated that PBRM1 functions as a tumor suppressor in bladder cancer by repressing cyclin B1 expression." (PMID 25978027, 2015). "We also observed that cyclin B1 was suppressed by PBRM1, indicating its tumor promoting effect in bladder cancer." (PMID 25978027, 2015). "PBRM1 maps to chromosome 3p21, a region where structural abnormalities were also frequently detected in bladder cancers, implying a strong potential tumor suppressor effect in bladder cancer." (PMID 25978027, 2015). "Taken together, these data indicated that PBRM1 played a role in regulating the G2/M transition of the cell cycle when introduced into bladder cancer cells." (PMID 25978027, 2015). "Our results showed that PBRM1 expression was significantly reduced in bladder cancer cells and tissues compared to their normal counterparts." (PMID 25978027, 2015). "To determine the signaling pathway through which PBRM1 mediates cell cycle regulation, we analyzed the protein levels of several cyclins (cyclin A2, D1, D3 and B1) in bladder cancer cells." (PMID 25978027, 2015). "The univariate analysis revealed that PBRM1 expression correlated significantly with the overall survival of bladder cancer patients (p = 0.007)." (PMID 25978027, 2015). "Further functional analysis demonstrated that PBRM1 suppressed bladder cancer cell proliferation, migration, colony formation in vitro and tumorigenicity in vivo." (PMID 25978027, 2015). "We assessed the expression of PBRM1 in 64 bladder cancer tissue samples with matching normal tissues." (PMID 25978027, 2015).